SPARCL1 (SPARC like 1)
Diseases named in the same sentence as SPARCL1 in open-access papers (continued):
Sharing a sentence is not in itself a finding about the gene and the disease.
cancer (continued). "Then the disease-free survival (DFS) analysis was performed to further assess the prognostic value of SPARCL1 across cancers." (PMID 36483097, 2022). "In this manuscript, we assessed the expression of SPARCL1 across cancers in the TIMER2.0 and GEPIA2 databases." (PMID 36483097, 2022). "Previous research has reported that down-regulated SPARCL1 occurred frequently in most human cancers and emerging publications have reported the potential role of SPARCL1 to reduce cell proliferation and inhibit DNA synthesis." (PMID 36483097, 2022). "Yet, the functional importance of SPARCL1 in epithelial carcinoma is still unclear, as does the importance of their interactions with macrophages." (PMID 36483097, 2022). "SPARCL1 interference reduced cell viability and increased the rate of apoptosis, yet in other studies, SPARCL1 inhibited cancer cellular proliferation." (PMID 34872433, 2021). "Secreted protein acidic and rich in cysteine-like 1 (SPARCL1) belongs to the SPARC-associated family of matricellular proteins and is frequently found to be decreased in a number of cancer types." (PMID 33897765, 2021). "In this study, careful selection of a retrospective advanced UTUC cohort, and in vitro cancer behaviour analysis proved the important role of SPARCL1 in UTUC." (PMID 30987093, 2019). "The mechanism of SPARCL1 in cancer behaviour in these studies involved cell growth, proliferation, differentiation, cell cycle inhibition, and regulation of the microenvironment." (PMID 30987093, 2019). "These merged DMxDE datasets suggest some known or previously reported/suspected cancer genes [PR: SPARCL1, NQO1, CST1, MELK1, DPT, FAM83A, MMP9; GB: FOXM1, TFAP2, GREM1, ITGA8, GRIA1, SLIT3] as well as many previously unreported genes/loci." (PMID 26683690, 2015). "Some of these cancer-related genes were associated with processes occurring in the extracellular matrix and related to DCN: CXCR4/CXCL12 axis, SELP, vWF, COL3A1, SCARA, SPARCL1." (PMID 26437222, 2015). "In summary, our study provides evidence SPARCL1 is downregulated in various cancer types." (PMID 39548034, 2024). "In addition, the product of the SPARCL1 gene affects the viability of cancer cells and exhibits anti-adhesion effects." (PMID 39685620, 2024). "In summary, our study highlights the multifaceted function of SPARCL1 in cancer biology." (PMID 39548034, 2024). "Our analysis revealed that SPARCL1 was downregulated across multiple cancers." (PMID 39548034, 2024). "As described, these results supported prognostic implications of SPARCL1 in pan-cancer." (PMID 36483097, 2022). "As TMB has emerged as a reliable predictor of immunotherapy response in many cancers, SPARCL1 might function as a biomarker in evaluating immunotherapy response." (PMID 36483097, 2022). "More researches are needed to explore the potential mechanism of SPARCL1 across cancers." (PMID 36483097, 2022). "Although SPARCL1 was down-regulated in most cancers, SPARCL1 might play a protective or detrimental role in different cancers." (PMID 36483097, 2022). "Additionally, we found a significant positive correlation between SPARCL1 and macrophage infiltration levels in most cancers." (PMID 36483097, 2022). "Although previous results indicated the potential prognostic value of SPARCL1 across cancer, its potential role is still unknown." (PMID 36483097, 2022). "Many studies have revealed the downregulated status and role of SPARCL1 in various cancers." (PMID 33980221, 2021). "The conclusion about the oncologic impact of SPARCL1 is similar in many other cancer studies." (PMID 30987093, 2019). "Much literature has been published describing the role of SPARCL1 in the prognosis many cancers." (PMID 30987093, 2019).
cancer (continued). "Considering down-regulated genes in LSC GFP+ cells, expression level of several of them inversely correlates with cancer aggressiveness, notably in prostate such as SPARCL1, a negative regulator of bud expansion and prostasphere growth, and SFRP1, a negative regulator of Wnt pathway." (PMID 27081082, 2016). "Sparcl1 expression is often found down-regulated in various cancer cells and it may act as a negative regulator of cell proliferation." (PMID 23209762, 2012). "In recent years, SPARCL1 has been extensively studied in cancer and could be a potential target for cancer therapy, and it has recently been reported that SPARCL1 regulates adipogenesis in mice, but the exact mechanism is unknown and there are limited studies in sheep lipid metabolic processes." (PMID 34872433, 2021). "Besides, SPARCL1 may be involved in the regulation of drug resistance in cancer." (PMID 35111844, 2022). "However, the mechanism of SPARCL1 in human cancers remains unclear." (PMID 35111844, 2022). "Results show that SPARCL1, CDH2, CP, HP, TF and SERPINA5 were all significant downregulated in cancer tissues (p < 0.05)." (PMID 34422629, 2021). "We found that SPARCL1, ENG, TAL1, ATP8A2 and HOXA9 were down-regulated in 99, 94, 89, 65 and 49% of the 82 cancer samples." (PMID 28178989, 2017). "The gene expression levels of SPARCL1 and TAL1 were down-regulated in all the eight cancer tissues compared with their paired adjacent normal tissues, while ENG was down-regulated in six of the eight cancer tissues." (PMID 28178989, 2017). "Moreover, SPARC-like protein 1 (SPARCL1), IQGAP1, BPIFA1, and cornulin are potential candidate proteins abnormally expressed in multiple types of cancers, especially LC." (PMID 36064415, 2022). "However, the potential functions of SPARCL1 in the pan-cancer cohort have not been widely studied." (PMID 36483097, 2022). "In addition, compared to liver metastatic cancer tissues, CP, HP, TF, and SERPINA5 were upregulated in normal liver tissues, while the expression CDH2 and SPARCL1 did not exhibit significant differences between the two tissues." (PMID 34422629, 2021).
infection (6 papers, 2017 to 2025). The state of being infected such as from the introduction of a foreign agent such as serum, vaccine, antigenic substance or organism. "Vascular cells shared six down-regulated DEGs in response to either Aβ pathology or MA10 infection, (Rgs5, Slc1a2, Flt1, Sparcl1, Bsg, Pecam1)." (PMID 41497643, 2025). "Levels of CXADR, BNIP3, and SPARCL1 mRNA were measured during the persistent phase of infection with Ad5dl309 (56–77 days p.i.)and normalized to the housekeeping gene EIF1." (PMID 41497616, 2025). "Curiously, repression of SPARCL1 by the virus was observed inconsistently in three separate infections." (PMID 41497616, 2025). "MA10 infection induced seven additional down-regulated (Hsp90aa1, Tcf7l2, Gnas, Sparcl1, Ywhag, Cpe, Sparc) and four upregulated DEGs (Ppp1r1b, Penk, Arpp21, Pcp4), whereas Aβ pathology resulted in five down-regulated (Cplx1, Syp, Meg3, Snhg11, Penk) and one upregulated DEG (Psen1)." (PMID 41497643, 2025). "Interestingly, at a very late stage of injury, 60 days post-infection, we observed high levels of SPARCL1 concentration only in the serum (compared to the uninjured condition), while in BALF, it nearly returned to baseline levels." (PMID 38762489, 2024). "The upregulation of growth factors and MMPs, derived in part from infiltrating macrophages and neutrophils, and the down-regulation of SPARCL1 are likely to contribute to matrix remodeling, collagen deposition and conjunctival scarring in the post-infection inflammatory phase." (PMID 28966918, 2017). "In agreement with previously reported results, infection reduced CXADR, BNIP3, and SPARCL1 expression to between 0.6% and 13% of the level detected in non-infected cells transduced with the empty vector." (PMID 41497616, 2025). "After two months of infection, the number of viral genomes was determined and the relative level of mRNA for CXADR, BNIP3, SPARCL1 and SLFN11 was measured in infected and mock-infected cells." (PMID 41497616, 2025). "We previously reported that expression of several cellular genes, including CXADR, BNIP3, SPARCL1, SLFN11, BBS9 and BNIP3, is significantly downregulated by epigenetic means during the persistent phase of infection of B cells." (PMID 41497616, 2025). "Notably, deficiency in endothelial Sparcl1 reduced the levels of the classical monocyte chemoattract CCL2 (also known as MCP-1) in BALF and serum (not significant) during infection (day 12)." (PMID 38762489, 2024).
metabolic disorders (4 papers, 2021 to 2022). "First, the cross-sectional study design cannot assess the causality of serum Sparcl1 and metabolism disorders." (PMID 36387870, 2022). "Although SPARCL1 has been intensively studied in the context of cancer, its role in AT and metabolic diseases has been reported only recently." (PMID 35909571, 2022).
gastrointestinal tumours (3 papers, 2020 to 2024). "SPARCL1 has been extensively investigated in gastrointestinal tumours." (PMID 39548034, 2024). "Another ECM molecule that modulates angiogenesis in the context of GI tumors is secreted protein acidic and rich in cysteine (SPARC)-like protein 1 (SPARCL1), a member of the SPARC family." (PMID 32456248, 2020).
SPARCL1 also shares sentences with these, for which no sentence is quoted: cardiovascular disease (4 papers); liver cancer (4); colon adenocarcinoma (3); amyotrophic lateral sclerosis (2); diabetes (2); head and neck squamous cell carcinoma (2); hyperlipidemia (2); hypertriglyceridemia (2); lung squamous cell carcinoma (2); Parkinson disease (2); prostate adenocarcinoma (2); stomach adenocarcinoma (2); thyroid carcinoma (2); uterine corpus endometrial carcinoma (2); acute myeloid leukemia (1); angina (1); bladder urothelial carcinoma (1); breast invasive carcinoma (1); carotid atherosclerosis (1); chronic lung disease (1); chronic myeloid leukemia (1); chronic pancreatitis (1); diffuse large B-cell lymphoma (1); endothelial dysfunction (1); esophageal cancer (1); esophageal squamous cell carcinoma (1); fibrosis (1); Huntington disease (1); Hypertension (1); ischemic heart disease (1).
A further 23 diseases each share a sentence with SPARCL1 in 1 paper.